ESM1 (endothelial cell specific molecule 1)
Diseases named in the same sentence as ESM1 in open-access papers (continued):
Sharing a sentence is not in itself a finding about the gene and the disease.
cervical cancer (continued). "The expression, biological functions and underlying molecular mechanisms of endothelial cell-specific molecule 1 (ESM1) in human cervical cancer remain unclear." (PMID 36522312, 2022). "In addition, cervical cancer cell proliferation was inhibited by the applied ESM1 shRNAs, leading to the significantly decreased percentage of EdU-positive nuclei." (PMID 36522312, 2022). "Together, ectopic ESM1 overexpression promoted cervical cancer cell progression in vitro." (PMID 36522312, 2022). "To verify the hypothesis, we further elucidated the stimulations of ESM1 to EMT in cervical cancer." (PMID 38954708, 2024). "Therefore ESM1 is upregulated in local cervical cancer tissues." (PMID 36522312, 2022). "ESM1 could be a novel and essential oncotarget protein for cervical cancer." (PMID 36522312, 2022). "In addition, we also explored the DEGs based on ESM1 expression in TCGA cervical cancer database." (PMID 36522312, 2022). "In addition, ESM1 KO dramatically suppressed cervical cancer cell in vitro migration and invasion." (PMID 36522312, 2022). "Moreover, ESM1 expression in cervical cancer cells was tested." (PMID 36522312, 2022). "The results showed that the co-expressed proteins with ESM1 could widely affect the cell adhesion, extracellular matrix organization, and mesenchymal cell differentiation, which indicated that ESM1 was likely to regulate the malignant progression of cervical cancer through EMT process." (PMID 38954708, 2024). "In summary, we demonstrated that ESM1 was correlated with the malignant progression of cervical cancer through ZEB1/EMT axis, and ESM1 was a key regulatory protein during the cervical cancer progression." (PMID 38954708, 2024). "Meanwhile, we further verified that the Aloe-emodin could directly target ESM1 to inhibit malignant progression of cervical cancer, which illustrated that aloe-emodin might be a potential drug and provided potential therapeutic strategy for clinical treatment of cervical cancer." (PMID 38954708, 2024). "SYT13 silencing potently inhibited ESM1-overexpression-induced PI3K-Akt cascade activation and cervical cancer cell migration/invasion." (PMID 36522312, 2022). "In cervical cancer cells, PI3K/Akt activation was largely inhibited by ESM1 shRNA or KO but was augmented following ESM1 overexpression." (PMID 36522312, 2022). "Therefore, ESM1-driven cervical cancer progression could be due to promoting SYT13 expression." (PMID 36522312, 2022). "In established and primary cervical cancer cells, ESM1 shRNA or CRISPR/Cas9-induced ESM1 KO hindered cell proliferation, cell cycle progression, in vitro cell migration and invasion, and induced significant apoptosis." (PMID 36522312, 2022). "Inhibitory effect of aloe emodin on ESM1/ZEB1/EMT signaling pathway and cervical cancer cells." (PMID 38954708, 2024). "Whereas siRNA-induced silencing of SYT13 decreased PI3K-Akt cascade in cervical cancer cells, without affecting ESM1 expression." (PMID 36522312, 2022). "Importantly, SYT13 silencing potently inhibited ESM1-overexpression-induced PI3K-Akt activation and cervical cancer cell migration/invasion." (PMID 36522312, 2022). "Thus, ESM1 overexpression is important for PI3K-Akt- mTOR activation and EMT in cervical cancer cells." (PMID 36522312, 2022). "However, whether ESM1 is related to the malignant progression and could mediate the EMT process in cervical cancer remain elusive, which needs for a comprehensive investigation." (PMID 38954708, 2024).
colon cancer (3 papers, 2018 to 2023). "Meanwhile, in vitro assays revealed that ESM1 and SLC10A2 exert opposing roles in colon cancer cell proliferation, validating the accuracy of the model." (PMID 33330631, 2020). "Furthermore, we attempted to validate the functional effects of ESM1 and SLC10A2 on colon cancer cells in vitro." (PMID 33330631, 2020).
Pleural effusion (3 papers, 2017 to 2023). The presence of an excessive amount of fluid in the pleural cavity. "In addition, several studies have shown high ESM1 expression not only in cancer tissues but also in serum and pleural effusion." (PMID 35937390, 2022). "However, the content of ESM-1 in pleural effusion is unclear." (PMID 28514746, 2017).
adenoma (2 papers, 2019 to 2021). A neoplasm arising from the epithelium. "We found that significant positive associations were noted between tumor size and both ESM-1 expression in vascular endothelial tissues and in adenoma tissues." (PMID 31455321, 2019). "However, only tumor size was associated with ESM-1 expression in adenoma tissues (P = 0.016)." (PMID 31455321, 2019). "The high expression rate of ESM-1 in vascular endothelial tissues (63/94, 67%) was significantly higher than that in adenoma tissues (49/94, 52%; P = 0.037)." (PMID 31455321, 2019). "In the present study, we specifically focused on one type of adenoma, namely null cell adenoma (NCA), and evaluated the relationship between invasion and ESM-1 expression both in vascular endothelial and adenoma tissues." (PMID 31455321, 2019). "ESM-1 expression was detected in both vascular endothelial tissues and adenoma tissues." (PMID 31455321, 2019).
cervical squamous cell carcinoma (2 papers, 2023). A squamous cell carcinoma arising from the cervical epithelium. "However, the exact significance of ESM1 in cervical squamous cell carcinoma (CSCC) is not yet well understood." (PMID 37476182, 2023).
chronic kidney disease (2 papers, 2017 to 2020). Impairment of the renal function secondary to chronic kidney damage persisting for three or more months. "Therefore, ESM1 may play an important role in the progression of chronic kidney disease and may serve as a marker for the clinical diagnosis of renal fibrosis." (PMID 32781625, 2020). "In non-dialysis chronic kidney disease patients (stage 5), circadian heart rate variability correlates positively with serum ESM1 concentration." (PMID 32781625, 2020).
gastric tumours (2 papers, 2019 to 2023). "ESM-1 is a biomarker associated with tumor progression in various types of tumors, including lung, liver, brain, kidney, and stomach tumors, and ESM-1 overexpression has been associated with poor prognosis." (PMID 31455321, 2019).
heart failure (2 papers, 2022 to 2024). Inability of the heart to pump blood at an adequate rate to meet tissue metabolic requirements. "There is a correlation between the ESM1 level and the occurrence of heart failure." (PMID 37968862, 2024). "ESM1 is an independent predictor of heart failure‐related events in chronic heart disease patients." (PMID 37968862, 2024).
hepatoblastoma (2 papers, 2014 to 2017). Hepatoblastoma (HB) is a malignant hepatic tumor and is the most common pediatric liver cancer. "A natural antisense association between downregulated lncRNA TCONS-00014512 and ESM1 may help us learn more about how lncRNAs regulate gene expression in hepatoblastoma." (PMID 24465615, 2014). "The expression of VEGF, ESM-1, and CD34 was positively associated with CRNDE levels in the hepatoblastoma tissues." (PMID 28178668, 2017). "Lastly, qRT-PCR data verified six upregulated and downregulated lncRNAs in hepatoblastoma, plus endothelial cell-specific molecule 1 (ESM1) mRNA." (PMID 24465615, 2014). "Indeed, a downregulated lncRNA (i.e., TCONS-00014512) in hepatoblastoma tissues was found to be located near ESM1." (PMID 24465615, 2014). "In addition, we verified the presence of some of these differentially expressed lncRNAs and ESM1 mRNA in hepatoblastoma tissues." (PMID 24465615, 2014).
Hyperglycemia (2 papers, 2017 to 2022). An increased concentration of glucose in the blood. "We speculate that the combination of maternal hyperglycemia and pre-gestational BMI, or pre-gestational BMI alone, regulate the gene expression changes of ESM1 and TSPAN14 in the adipose tissue of GDM offspring." (PMID 35740266, 2022). "It is noteworthy that the O-T1D group was also characterized by having leaner mothers, which suggests that other factors implicated in GDM, such as increased inflammation or lifestyle, and not mere hyperglycemia, may play a role in the epigenetic reprogramming of ESM1 and TSPAN14." (PMID 35740266, 2022).
ischemic stroke (2 papers, 2018 to 2024). A stroke disorder caused by obstruction of blood flow to the brain, due to thrombotic (local blood clot formation) or embolic (due to a blood clot or other material traveling from another site) event. "LncRNA TCONS_00097976 is connected to angiogenesis-related miR-92b-3p and angiogenesis-related genes Esm1, Angptl2, and Stat3, which have been reported differently expressed in ischemic stroke." (PMID 29516010, 2018).
leiomyoma (2 papers, 2007). A well-circumscribed benign smooth muscle neoplasm characterized by the presence of spindle cells with cigar-shaped nuclei, interlacing fascicles, and a whorled pattern. "The expression of many components of ECM including collagens, decorin, versican, fibromodulin, intergrins, extracellular matrix protein 1 (ECM-1), syndecan and ESM-1 has been identified in leiomyomas as well as dermal wounds during healing, scars and keloids." (PMID 17718906, 2007). "We validated the expression of ECM-2, ESM1, THBS1, FBLN5 and COL18A1 in keloids, incisional scars and adhesions and the analysis indicated an elevated expression of ECM2, THBS1 and FBLN5 in keloid/incisional scars and COL18 in peritoneal adhesions as compared to leiomyomas." (PMID 17718906, 2007).
melanoma (2 papers, 2018 to 2022). A malignant, usually aggressive tumor composed of atypical, neoplastic melanocytes. "Similar to our data from melanoma cell lines, we observed some VEGF targets in the top 65 DEGs, such as CHI3L1, KLF1 and ESM1." (PMID 30242167, 2018).
migraine (2 papers, 2023 to 2024). "Elevated levels of MMP-9 and ICAM-1 as well as endothelial cell-specific molecule-1 (ESM-1) and claudin-5 have been observed in migraine patients supporting the involvement of BBB disruption during attacks." (PMID 37596546, 2023).
myeloid leukemia (2 papers, 2020 to 2023). A clonal proliferation of myeloid cells and their precursors in the bone marrow, peripheral blood, and spleen. "Previous studies have reported that ESM1 could accelerate myeloid leukemia cell 45, BRCA cell 20 and NSCLC cell 17 proliferation, as well as promote the apoptosis escape of CRC cells 46, myeloid leukemia cells 45, and BCA cells." (PMID 36594088, 2023). "Downregulation of ESM-1 in myeloid leukemia cells inhibits proliferation and promotes apoptosis." (PMID 33489036, 2020).
oral cancer (2 papers, 2015 to 2018). "Querying the TCGA HNSCC dataset we identified 8 potential mRNA targets (ESM1, KLF4, IL8, CCL20, IL24, CCNA1, TIMP4 and MMP1) from our validated 20 mRNA panel, which were aberrantly expressed in HNSCC and controlled by CELF1 in oral cancer cells." (PMID 26498364, 2015).
Stroke (2 papers, 2016 to 2022). Sudden impairment of blood flow to a part of the brain due to occlusion or rupture of an artery to the brain. "Endothelial cell-specific molecule 1 (Esm1) has dual effects on angiogenesis and inflammation, and the research has shown that knockout Esm1 can reduce vascular permeability and cerebral edema following stroke." (PMID 36052309, 2022). "Five were the targetgenes of let-7 (ESM1, VIM, CDK6, NRAS, and KRAS), 3 of which (ESM1, VIM, and CDK6) were correlated with stroke based on published literatures." (PMID 26830013, 2016). "Finally, ESM1, KRAS, miR-181d, miR-181b-3p, miR-605-3p and miR-605-5p were highly expressed in the blood of stroke patients compared to healthy people." (PMID 26830013, 2016).
acute kidney injury (1 paper, 2022). Sudden and sustained deterioration of the kidney function characterized by decreased glomerular filtration rate, increased serum creatinine or oliguria. "Six hub genes (MDFI, EHBP1L1, FBXW4, MDM4, RALYL, and ESM1) were identified as potentially predictive of an acute kidney injury." (PMID 36313991, 2022). "The expression of ESM1 and RALYL were markedly increased in control samples, while EHBP1L1, FBXW4, MDFI, and MDM4 were markedly increased in acute kidney injury samples." (PMID 36313991, 2022).
adrenocortical adenomas (1 paper, 2021). "In ACC, the combined ESM1 score was significantly higher than that in adrenocortical adenoma and normal adrenal tissues (p < 0.001)." (PMID 34858850, 2021). "In adrenocortical adenomas, ESM1 was a strong cytoplasmic expression and weak membrane expression." (PMID 34858850, 2021). "In adrenocortical adenomas, ESM1 was mainly cytoplasmic positive and faint membrane positive." (PMID 34858850, 2021). "In adrenocortical adenomas, ESM1 has a strong cytoplasmic expression and weak membrane expression." (PMID 34858850, 2021). "In normal adrenal cortex, adrenocortical adenoma (benign tumor), and ACC (malignant tumor), IHC staining suggested that ESM1 was diffuse cytoplasmic and membrane positive in ACC." (PMID 34858850, 2021). "Thus, it suggested that ESM1 could be viewed as a biomarker to make a distinction between ACC and adrenocortical adenoma or normal adrenal cortex tissues." (PMID 34858850, 2021).
aneurysm (1 paper, 2021). Bulging or ballooning in an area of an artery secondary to arterial wall weakening. "A previous study showed that the total aneurysm volume was positively correlated with endocan (endothelial cell-specific molecule-1—ESM-1) concentration." (PMID 34572455, 2021).
aortic atherosclerosis (1 paper, 2024). A atherosclerosis that involves the aorta. "Serum ESM1 levels in patients with aortic atherosclerosis strokes are significantly increased." (PMID 37968862, 2024).
cutaneous melanoma (1 paper, 2019). A primary melanoma arising from atypical melanocytes in the skin. "Our study also proposes genes ESM1, NFATC3, C7orf4, CDK14, ZNF827, and ZSWIM7 as novel putative markers for cutaneous melanoma metastasis." (PMID 31673075, 2019).
dementia (1 paper, 2025). Loss of intellectual abilities interfering with an individual's social and occupational functions. "Similarly, proteins such as MMP8, IL32, NDRG1, SMOC2, or ESM1, which have been previously reported to contribute to AD pathology, showed to be significantly increased in both MCI A + T + and AD dementia, but not in MCI A-T-, suggesting a specific AD-related signature in pEVs proteome." (PMID 41282153, 2025).
diabetic macular edema (1 paper, 2025). "It has also been suggested that diabetic macular edema, a major cause of visual impairment apart from retinopathy, is linked to elevated blood ESM-1 levels." (PMID 41578817, 2025).
diabetic retinopathy (1 paper, 2025). "This suggests that serum ESM-1 levels may increase in accordance with the Diabetic Retinopathy (DR) stage and that ESM-1 may serve as a marker for DR progression." (PMID 41578817, 2025).
emphysema (1 paper, 2020). "So, we surmised that reduction of ESM-1 expression would induce destruction and insufficient repair of lung tissue, leading to development of emphysema." (PMID 33489036, 2020).
endometrial cancer (1 paper, 2022). Primary or metastatic malignant neoplasm involving the endometrium (mucous membrane that lines the endometrial cavity). "We aimed to study the function and mechanism of endothelial cell-specific molecule 1 (ESM1) in endometrial cancer (EC)." (PMID 36117773, 2022).
endometriosis (1 paper, 2025). The growth of functional endometrial tissue in anatomic sites outside the uterine body. "In the GSE141549 validation cohort, only DDR2, ESM1, and PRKAB1 maintained the same expression trends as observed in the merged dataset, with statistically significant differences between normal and endometriosis samples (DDR2, p < 0.001; ESM1, p = 0.002; PRKAB1, p < 0.001)." (PMID 41424583, 2025). "In the merged dataset, the expression levels of these six genes—DDR2, ENO3, ESM1, NMBR, PRKAB1, and PRPF19—showed significant differences between normal and endometriosis samples (DDR2, p < 0.001; ENO3, p < 0.001; ESM1, p < 0.001; NMBR, p = 0.002; PRKAB1, p < 0.001; PRPF19, p < 0.001)." (PMID 41424583, 2025).
esophageal squamous cell carcinoma (1 paper, 2022). Esophageal squamous cell carcinoma (ESCC) is a type of esophageal carcinoma (EC) that can affect any part of the esophagus, but is usually located in the upper or middle third. "However, the potential role of ESM1 in esophageal carcinogenesis (ESCA)/esophageal squamous cell carcinoma (ESCC) is still unclear." (PMID 35937390, 2022).
esophageal tumors (1 paper, 2022). "Subsequently, the expression level of ESM1 in surgical esophageal tumors and adjacent normal tissues was detected by qRT–PCR and immunofluorescence." (PMID 35937390, 2022).
hypopharyngeal cancer (1 paper, 2019). Carcinoma, predominantly squamous cell, arising from the epithelial cells of the hypopharynx. "Because these results from TCGA data were at the RNA level, we then detected ESM1 expression at the protein level in the 21 laryngeal or hypopharyngeal cancer samples." (PMID 31073279, 2019).
Lewis lung carcinoma (1 paper, 2022). "Other models include Esm1-Cre, which while commonly associated with the study of sprouting angiogenesis in the postnatal retina, reports have demonstrated its ability to study tumor angiogenesis in the Lewis lung carcinoma model." (PMID 36970722, 2022).
malignant glioma (1 paper, 2017). A grade III or grade IV glioma arising from the central nervous system. "HULC can promote the angiogenesis, one hallmark of malignant gliomas, by inhibiting the expression of angiogenesis-related molecule ESM-1 (endothelial cell specific molecule 1)." (PMID 28293170, 2017).
metastatic prostate carcinoma (1 paper, 2022). A carcinoma that arises from the prostate gland and has spread to other anatomic sites. "A very recent study reported that ESM1 overexpression was associated with poor overall survival in metastatic prostate cancer." (PMID 36522312, 2022).
metastatic tumor (1 paper, 2021). "An interesting observation is that ESM-1 mRNA level is much higher in metastatic tumor samples than in non-metastatic tumor samples, indicating that ESM-1 expression is associated with metastasis." (PMID 34109132, 2021).
nasopharyngeal carcinoma (1 paper, 2018). A carcinoma arising from the nasopharyngeal epithelium. "Moreover, ESM1 has been related to shorter survival in e.g., breast, liver, and nasopharyngeal cancer, but has not been investigated in OPSCC." (PMID 29587383, 2018).
Neonatal sepsis (1 paper, 2023). Systemic inflammatory response to infection in newborn babies. "The aim of this study was to determine the potential of early inflammatory markers to diagnose late-onset neonatal sepsis—procalcitonin (PCT), interleukin 6 (IL-6), interleukin 8 (IL-8) and endocan (ESM-1)." (PMID 37755410, 2023). "According to our results, ESM-1 and IL-8 are not reliable markers of late neonatal sepsis." (PMID 37755410, 2023).
pancreatic cancer (1 paper, 2025). "ESM1 encodes a secreted protein that is mainly expressed in endothelial cells; it regulates the proliferation, migration, invasion and drug resistance of tumor cells, thereby promoting tumor progression and metastasis and playing an important role in the pathogenesis of pancreatic cancer." (PMID 40362181, 2025). "Among the nineteen UDEGs, other than the seven UDEGs reported to be carcinogenic and prometastatic genes involved in pancreatic cancer, the other UDEGs, such as ESM1, PCDH7, CORO2A, CEACAM5, GALNT5 and TMPRSS4, are also involved in other cancers." (PMID 40362181, 2025).
papillary thyroid carcinoma (1 paper, 2024). "The outcomes of these experiments are anticipated to constitute a foundational step towards characterizing ESM1’s role in the etiology and progression of papillary thyroid carcinoma, with broader implications for the development of innovative diagnostic and therapeutic strategies." (PMID 38626010, 2024). "However, the function of ESM1 in papillary thyroid cancer (PTC) is not well understood." (PMID 38626010, 2024).